TNF (tumor necrosis factor)
Diseases named in the same sentence as TNF in open-access papers (continued):
Sharing a sentence is not in itself a finding about the gene and the disease.
tumor (continued). "This patch when administered to colon cancer induced mice, stimulated the skin residing antigen presenting cells that subsequently resulted in suppression of the tumour growth through elevated levels of TNF-α and IFN-γ." (PMID 36851335, 2023). "To assess the role of these cytokines in AS, we treated tumor-bearing mice with CAR T-vax therapy in the presence of neutralizing antibodies against IFN-γ or TNF-α." (PMID 37413990, 2023). "The antitumor potential of M1-like TAMs is based on the lysis of tumor cells after phagocytosis or on the secretion of immunostimulatory cytokines and chemokines (e.g., IL-6, IL-12, TNF) which induce inflammation and thus tumor suppression." (PMID 36672212, 2023). "In this context, IL-17 A cytokine is the mostly known as pro-angiogenic mediator now a days, due to its involvement in inflammatory process and TNF-alpha secretion in tumor microenvironment." (PMID 37563607, 2023). "TNF-α is another pro-inflammatory cytokine that is produced by tumor or inflammatory cells and is involved in the regulation of a variety of signaling processes." (PMID 38075864, 2023). "It is induced by many inflammatory cytokines like TGF-β, TNF-α, IL-1, and IL-6, influencing inflammation in cancer, by which the desmoplastic response of tumors involves an interplay between the invading tumor cells and the altered extracellular matrix." (PMID 36742380, 2023). "TNF-α is produced by cancer cells as well as the tumor microenvironment and can function as both pro-survival and pro-apoptotic factors based on its level of expression." (PMID 37867861, 2023). "Studies using a Drosophila melanogaster malignant tumour model have demonstrated that TNF and IL-6 mediated autophagy can modulate the tumor microenvironment and participate in tumor growth." (PMID 37313458, 2023). "As TRAF2 is required to interact with cIAP1 or cIAP2 to promote TNFR1‐induced NF‐κB signalling and suppress TNF‐induced cell death, inhibition of TRAF2 or cIAPs is necessary to sensitise tumour cells to TNF‐induced cell death." (PMID 36881608, 2023). "In the present study, we found that the level of proinflammatory cytokines including IL-1β, IL-6 and TNF-α were significantly increased in tumor-bearing mice after DSF treatment." (PMID 37305383, 2023). "Factors such as IL-8, VEGF, PDGF, NGF, SCF, and histamine promote tumor growth, while IL-1, IL-6, TNF-α, and fibroblast proteases inhibit tumor growth." (PMID 37686677, 2023). "In this study, NF-κB p65 (RelA) and TNFα were found to be highly expressed in many tumor types, including GBM from global databases." (PMID 37892820, 2023). "Spätzle activates the Drosophila fat body tumor necrosis factor, Eiger, which leads to tumor cell death via apoptosis." (PMID 36831266, 2023). "It is a cytokine with potent anti-inflammatory properties by repressing the expression of inflammatory cytokines, such as TNF-α, IL-6, and IL-1 and is considered one of the most crucial immunosuppressive cytokines in tumor progression." (PMID 36835413, 2023). "M1 macrophages exhibit enhanced antigen-presenting activity while secreting CXCR3 ligands (CXCL9, CXCL10, CXCL11) and CXCL16 to recruit Th1 and NK cells and secrete TNF-α, synergistically exerting anti-tumor functions." (PMID 37063892, 2023). "A significant decrease in the levels of TNF-α present in the sera of BALB/c mice implanted with the F3II tumor was observed when treated with 6.25 (p < 0.01); 12.5 (p < 0.01) and 25 mg/kg (p < 0.05) of H. junceus scorpion venom." (PMID 38137888, 2023). "Mechanistically, TNF-α induced autophagy and prevented energy transfer from the tumour microenvironment." (PMID 37162544, 2023). "It was also shown that CAFs strongly mediated tumor angiogenesis by secreting immunomodulatory and pro-angiogenic cytokines and chemokines, such as IL-4, IL-6, IL-8, TNF-α, TGF-β, VEGF, and SDF-1." (PMID 37686315, 2023).
tumor (continued). "Serum and intratumoral levels of TNFα are strongly elevated in RCCs, compared to other cancer types, and correlated with tumor size." (PMID 37190141, 2023). "NK cells are produced mainly in the bone marrow, and when they are in touch with tumor cells, they secrete cytokines like cytolytic TNF-α and IFN-γ." (PMID 37108109, 2023). "Activated CAR T cells predominantly kill tumor cells through the secretion of granzymes and perforin and or via the engagement of their membrane-bound tumor necrosis factor (TNF) family ligands with the tumors’ receptors counterpart to induce apoptosis." (PMID 37998743, 2023). "TNF-α is an inflammatory factor secreted by macrophages and tumor cells and is also reported to be essential for cachexia-induced muscle atrophy." (PMID 37217930, 2023). "TRAIL is a member of the tumor necrosis factor (TNF) family that activates an apoptotic program in a broad variety of tumor cells upon binding to its pro-apoptotic receptors, sparing most normal cells." (PMID 37830584, 2023). "Accordingly, it was furthermore reported that TRAF2-deficiency and treatment with TWEAK or IAP antagonists sensitize for tumor cell killing by CD8+ T cell/NK cell-derived TNF." (PMID 38020877, 2023). "Cu2+ can also directly activate various angiogenic factors, including VEGF, fibroblast growth factor 2, TNF-α, and IL-1, thereby promoting tumor angiogenesis." (PMID 37064872, 2023). "The primary role of IFN-γ is to restrict viral propagation and tumour progression, whereas TNF-α and IL-2 further induce functional maturation in NKC and promote the growth and development of other immune cells, yielding a more robust immune response." (PMID 37687141, 2023). "Taken together, these findings indicate that serum sTIE2, PlGF, IL-6, IL-8, and TNF-α are biomarkers of tumor progression, vascular abnormalities, and immune suppression in GC." (PMID 37577519, 2023). "Hypoxia generally causes cell necrosis, leukocyte infiltration, and the release of TNF-α and IL-6 in tumor cells." (PMID 36837487, 2023). "Whilst still being fully elucidated, TNFα is known to have a role in tumour-promoting immune signalling via the induction of NF-kB." (PMID 37240301, 2023). "Likewise, a fully controlled response may be associated, for instance, with the counteraction of tumor-induced cachexia and the inhibition of catabolic pathways (IL-6, TNF-alpha) balanced with the stimulation of anabolic pathways (FoxO3a, p-AKT, p-mTOR, and P-GSK-3β)." (PMID 37895979, 2023). "Tumor-promoting immunosuppressive activity of FAP+ fibroblasts is connected with the inhibition of TNFα signaling." (PMID 36793444, 2023). "For example, metastatic tumor growth can be induced by TNFα release from host hematopoietic cells that mediates NF-κB activation in tumor cells." (PMID 37628724, 2023). "Regulates gut microbiota composition,CD8+ T-cell and Gr-1+ macrophagemediated immune suppression↑,TNF-α and NF-κB-mediated inflammation↓,regulates tumor immune microenvironment." (PMID 36817459, 2023). "Upregulate ZO-1, occludin, CD8 CTLs, ATP, and glucose of tumor-infiltrating lymphocytes; downregulate TNF-α, IL-1β, and PD-1." (PMID 38068759, 2023). "More importantly, recombinant TNF-α (rTNF-α) can rapidly destroy tumor blood vessels, eliminate hypertension inside tumors, disrupt tumor tissue growth, and activate CD8+ T cells." (PMID 37483629, 2023). "This is based on the rationale that high levels of TNFα promote tumour rejection, while chronic low levels of sustained TNFα expression, as seen in the tumour microenvironment, instead promotes tumorigenesis." (PMID 37455828, 2023). "The expression of TNF-α in the tumor microenvironment is a common feature of numerous malignant tumors, and it can promote the metastasis and invasion of various kinds of tumor cells." (PMID 36874003, 2023). "The COL6 ETP peptide was found to promote tumor inflammation by increasing macrophage recruitment and upregulating inflammatory factors such as IL-6 and TNF-α." (PMID 37476379, 2023).
tumor (continued). "Shifting focus to the impact of MDSC-derived TNF in the PDAC tumor microenvironment, the study unveiled its crucial role in immunoregulatory circuitries and stromal inflammation." (PMID 37455286, 2023). "Taking advantage of tumor cell heterogeneity, we provide proof-of-concept analyses of mechanisms of TNF resistance." (PMID 37398651, 2023). "In murine models, TIGIT+ NK cells recovered from either spleen or tumors of tumor-bearing mice had a lower frequency of IFNγ-, TNFα-, or DNAM-expressing cells as compared to TIGIT− NK cells." (PMID 37345049, 2023). "In this study, we designed an ensemble learning model to identify genes involved in NFκB-regulated pathways downstream of TNF and carcinogenesis by using mRNA expression profiles of tumor patients as features." (PMID 37475016, 2023). "M1‐TAMs are associated with inflammatory factors, including CCL2/3/4, CXCL3, and TNF, which recruit T cells, immature DCs, and NK cells in the tumor microenvironment." (PMID 36529697, 2023). "The presence of tumor cells in the D. melanogaster body activates a cellular response, which leads to release of Eiger, i.e., a Tumor Necrosis Factor (TNF), from hemocytes." (PMID 36982826, 2023). "The secretion of pro-inflammatory factors such as TNF-α, IL-1β and IL-6 regulated the tumour microenvironment and exerted anti-tumour effects." (PMID 37386139, 2023). "M1 macrophages promote tumor destruction and produce TNF and interleukin-6, while M2 macrophages contribute to tumor progression by producing VEGF, MMP, and interleukin-10." (PMID 37280670, 2023). "In human BC cells, TNF-α causes the secretion of MMP-9, which accelerates tumor invasion and metastasis." (PMID 36614308, 2023). "We conclude that low-dose interleukin-2 and tumor necrosis factor-a immunotherapy can mediate tumor regression while posing manageable harm." (PMID 36874133, 2023). "M1 macrophages produce various pro-inflammatory cytokines, such as tumor necrosis factor-alpha (TNF-α), interleukin-1 beta (IL-1β), and interleukin-6 (IL-6), which have been shown to inhibit tumor growth." (PMID 37999824, 2023). "After laser irradiation, M@C-HA/ICG increased TNF-α and IL-2 production in the 4T1 tumor-bearing model." (PMID 36986636, 2023). "Members of the tumor necrosis factor (TNF) superfamily are important inducers of apoptosis, contributing to the death response in tumor cells." (PMID 38026933, 2023). "M1 macrophages are activated by interferon-γ (IFN-γ), bacterial lipopolysaccharide (LPS), or tumor necrosis factor-α (TNF-α) and release interleukin 12 (IL-12) to prevent tumor growth." (PMID 36793738, 2023). "TNFα expression in splenic HSPCs of PyMT-B6-bearing mice hints at the presence of tumor-derived upstream mediators." (PMID 37134077, 2023). "DEX treatment also decreased the levels of pro-inflammatory cytokines, including IL-1β, TNFα, IL-10, and IL-18, which are major tumor growth promoters." (PMID 37528154, 2023). "TNF-α possesses pleiotropic effects in promoting angiogenesis, tumour-promoting inflammation and resistance to tumour cell apoptosis." (PMID 35708739, 2023). "In a murine HCC study, incomplete RFA initially stimulated residual tumor cells to produce CCL2 through the upregulation of TNF-α, contributing to the infiltration and activation of TAMs." (PMID 36831664, 2023). "We anticipate that the roles of TNFα and IL-1β in cisplatin-induced tumour vascular damage will be further investigated in the future." (PMID 37056922, 2023). "Subsequently, the reactivated T cells (CTL) carry out tumor antigen-specific cytolytic activity (ASIR) by releasing cytokines such as interferon (IFN)-γ/tumor necrosis factor (TNF)-α, perforin, and granzyme, which eradicate cancer cells." (PMID 36992219, 2023). "Phenotype M1 is able to directly kill tumor cells by producing nitric oxide and reactive oxygen species, or by secreting pro-inflammatory cytokines such as tumor necrosis factor-α (TNF-α), IL-6, and IFN-γ." (PMID 37513975, 2023).
tumor (continued). "TNF enhances tumor cell growth, invasion, proliferation, and tumor angiogenesis, as well as metastasis." (PMID 36874133, 2023). "We also observed a higher frequency of tumor-infiltrating CD8 + T cells expressing TNF-α and IFN-γ in the combination treatment group than in the individual anti-TIGIT or RT groups." (PMID 35794399, 2023). "Functionally, neoadjuvant chemotherapy induces proinflammatory cytokines and decreases pro-tumor cytokines from tumor-infiltrating T cells, with enhanced TNF-α and IL-2 and reduced IL-4 and IL-10 expression." (PMID 37173915, 2023). "M1 macrophages release proinflammatory cytokines, such as TNF-α, along with IL-1β, and IL-6, to activate innate immunity and kill tumor cells." (PMID 36902456, 2023). "Another known mechanism is tumor-derived TNF-α upregulating PD-L1 expression in the mast cells, representing a mechanism of immune suppression via the direct interaction between MCs and T lymphocytes in a PDL1-dependent manner." (PMID 37190096, 2023). "TNF-α is produced in lymphocytes and has been reported to induce tumor necrosis or improve resistance to infection by foreign antigens by acting alone or in combination with IL-1β in an in vivo immune response." (PMID 36874224, 2023). "CD8+ T lymphocytes mediate cytotoxic responses by releasing inflammatory factors like Interferon-gamma (IFN-γ) and TNF-α, inhibiting tumor growth, proliferation, and metastasis." (PMID 37901310, 2023). "PepO-primed M2 macrophages decreased the expression of tumor-supportive molecules like Arg-1, Tgfb, Vegfa and IL-10, and increased the expression of iNOS, Cxcl9, Cxcl10, TNF-α and IL-6 to inhibit TNBC growth." (PMID 37925462, 2023). "Mast cells can generate trypsin, TNF, IL-1, IL-6, and other factors to boost anti-tumor inflammatory responses, stimulate tumor cell apoptosis, and suppress cancer cell invasion." (PMID 37719863, 2023). "The treatment increased the number of CD8+ T cells infiltrating the tumor and increased levels of IFN-γ, GZMB, and TNF-α while decreasing the number of Treg cells in the tumor, blood, and spleen." (PMID 37397393, 2023). "In vitro neutralizing TNFα was observed to inhibit tumor progression and improve the curative effect of bevacizumab." (PMID 37787041, 2023). "When a tumor is removed, local inflammation occurs, and inflammatory cytokines like tumor necrosis factor (TNF)-α are released." (PMID 38258033, 2023). "Binding of their TCR ligands activates γδ T cells to secrete IFN-γ, TNF-α and other cytotoxic effector molecules that act against tumor cells (left)." (PMID 38274800, 2023). "Taking into account the satisfactory tumor–to–blood ratio of many immunocytokines, the appearance and development of TNF-based antibody fusion proteins seems only natural." (PMID 36839658, 2023). "Exhausted cytotoxic T cells are unable to lyse tumor cells, they have impaired effector functions and they show an inability to product pro-inflammatory cytokines (e.g., TNF-alpha, IFN-gamma, IL-2)." (PMID 37427115, 2023). "T cells are the primary agents responsible for anti-tumor immune response, executing it by death ligand-induced apoptosis or secretion of IFN-γ and TNF-α to induce tumor cells’ cytotoxicity." (PMID 37373091, 2023). "These included MMP3, with the corresponding gene also found to be amplified in the primary tumour, and the proinflammatory cytokine TNF-α." (PMID 37045997, 2023). "On the contrary, combining high-power MWA with anti-programmed death (PD)-1 therapy promoted CD8+ T-cell infiltration, reduced regulatory T-cell infiltration, upregulated a Th1-type cytokine (TNF-α) in peripheral blood, and inhibited distant tumor growth." (PMID 38139799, 2023). "TIDC have been shown to serve as tumor suppressors in the early stages by secreting pro-inflammatory cytokines such as TNF-α, IL-1, IL-12, and IL-23, but as tumor promoters in the later stages." (PMID 36771154, 2023).
tumor (continued). "Eosinophils are thought to amplify the Th1 immune response indirectly by promoting macrophage M1 skewing via IFN-γ and TNF-α production as well as contribute to the normalization of tumor vasculature resulting in tumor rejection." (PMID 37903733, 2023). "Tumor necrosis factor α (TNF-α), originally known as cachectin, promotes the malignancy potential and adhesion of tumor cells to vascular endothelial or lymphatic endothelium, thus increasing lymphatic or blood-transfer metastasis." (PMID 38068319, 2023). "Increased inflammatory cytokine level of TNF-α can promote the killing of cancer cells and amplify the proliferation of anti-tumor immune cells like CD8 + T cells and NK cells." (PMID 36138265, 2023). "Albumin synthesis decreases in response to the production of some inflammatory factors involved in tumor immunity and the acute phase response, such as tumor necrosis factor, interleukin-6, and C-reactive protein (CRP)." (PMID 37576904, 2023). "In another instance, Salmonella mutant strain ΔppGpp enhanced production of TNF- α and IL-1β by macrophages and dendritic cells within tumor cells and induced tumor cell apoptosis." (PMID 38090593, 2023). "Both TNF-α and IL-6 have been shown to be classical indicators of macrophage activation and in vivo demonstrated to mediate tumor promotion in various human cancers." (PMID 37784035, 2023). "Recent studies show that TNF-α is one of the key mediators of cancer-related inflammation and acts as a tumor-promoting factor." (PMID 37711747, 2023). "Genetic depletion of FAP allows considerable immunological control of tumors due to the rapid hypoxic necrosis of both cancer and stromal cells via IFN-γ and TNF-α, leading to enhanced infiltration and anti-tumor capacities of T cells." (PMID 37723510, 2023). "Release of cytokines such as TNF-α and IL-6 following NF-κB activation activates pro-survival signals in tumor cells and promotes growth and progression." (PMID 37005447, 2023). "Consistent with this theory, in a TRAF−/− melanoma mouse model, tumor cells redirected the TNF signaling pathway to favor RIPK1-dependent necroptosis, enhance tumor eradication, and show a better response to anti-PD-1 therapy than the control group." (PMID 36635765, 2023). "Unfortunately, our initially implemented non-target control in two independent experiments also led to a significant downregulation of vault RNA1-1 loading specifically under TNFα stimulation in the BON tumor model." (PMID 36980669, 2023). "TAMs as one of the main tumor-infiltrating immune cells produce pro-inflammatory cytokines, such as NF-κB p65, IL-1β and TNF-α and promote the development of CRC." (PMID 36774343, 2023). "The level of IL-1β, IL-6 and TNF-α were increased in tumor mice after DSF treatment, while the level of IL-4, IL-10 and TGF-β were increased after DSF treatment." (PMID 37305383, 2023). "As a result, the Smac-TLR7/8 hydrogel improved the anti-tumor activities of the macrophages, directed the phagocytosis of tumor cells, and increased the secretion of TNF." (PMID 36721212, 2023). "Strong and diffuse staining was observed, indicating that TNFα was secreted and dispersed around the tumor islets and stromal areas." (PMID 36420735, 2023). "TNF-α levels positively correlated to tumor size (R = 0.2624, p<0.05) and negatively to lymph nodal invasion (R = -0.2633, p<0.05)." (PMID 37942322, 2023). "Higher levels of effector cytokines IFNγ and TNFα and tumor‐infiltrated CD45+ immune cells after 8FNs vaccination indicated that 8FNs better rejuvenated the immunosuppressed microenvironment compared to aluminum salts‐adjuvanted vaccines." (PMID 37162249, 2023). "TNF signaling is relevant for cancer tumor progression and metastasis as well as acquired drug resistance." (PMID 37024452, 2023).